TNF (tumor necrosis factor)
Diseases named in the same sentence as TNF in open-access papers (continued):
Sharing a sentence is not in itself a finding about the gene and the disease.
Obesity (continued). "In the present study, the inflammatory marker, TNFα, was markedly increased in overweight children along with a significant reduction in UCN1 expression, especially in children with obesity." (PMID 35276788, 2022). "In obesity, adipocytes become hypertrophic and dysregulated, resulting in inflammatory changes in adipose tissue with the secretion of interferon-γ (IFN-γ) and TNF-α." (PMID 36552805, 2022). "IL-6, IL-8, IL-15, TNF-α, MCP-1 (CCL2) and other molecules, such as fibroblast growth factor 21, irisin, myonectin, and myostatin, are involved in obesity with insulin resistance or type 2 DM." (PMID 36552805, 2022). "Pro-inflammatory TNF-α has been shown to induce LCN2; the adipokine LCN2 has been positively correlated with obesity and is reported to mediate insulin resistance in humans." (PMID 36329549, 2022). "Other mechanisms are involved in obesity-derived hepatocarcinogenesis, including alterations in the signaling pathways of IL-6, PTEN, NF-κB, Hedgehog, TNF-α, and STAT3." (PMID 36612019, 2022). "During obesity, adipose tissue produces cytokines such as IL1ß, IL6, IFNγ, TNFα, MCP1, promoting chronic inflammation." (PMID 35422689, 2022). "Previous studies have indicated that the plasma concentrations of proinflammatory cytokines, such as TNF α, and IL6 are elevated under conditions of insulin resistance in obesity and type 2 diabetes (Dandona, Aljada & Bandyopadhyay, 2004)." (PMID 36213511, 2022). "Conversely, the pro-inflammatory cytokine TNF-α downregulates the levels of β-Klotho and induces inflammation, thus impairing the beneficial effects of FGF21 on obesity and ER stress." (PMID 35909571, 2022). "Endurance exercise intervention (ApoE WD EX) significantly alleviated atherosclerotic syndrome by reducing obesity, significantly inhibiting VCAM-1, MCP-1, TNF-α, and IL-1β expression, and increasing the production of SCFAs." (PMID 35256637, 2022). "Tumor necrosis factor (TNF) is one example of a pro-inflammatory cytokine and the first ’adipokine’ reported to be created by adipose tissue, regulated in obesity and related to obesity-related metabolic disease." (PMID 36282842, 2022). "By the correlation analysis, we identified 35 key genera, which were significantly correlated with features of obesity (body weight gain), dyslipidemia (TC, TG, HDL‐C, and LDL‐C), proinflammatory cytokines (serum IL‐6, IL‐1β, and TNF‐α), and LPS." (PMID 36348812, 2022). "Mechanistically, BATF3-deficiency caused adipose tissue inflammation characterized by an increase in M1-like adipose tissue macrophages and TNFα expression and a decrease of invariant NKT (iNKT) cells that precedes the development of obesity." (PMID 35812447, 2022). "The major intracellular stress kinase that links TNFα to inhibitory serine phosphorylation of IRS-1 in T2DM and obesity is the c-Jun N-terminal kinase (JNK) family of MAPK." (PMID 34070553, 2021). "Macrophages in CLS produce inflammatory mediators, including TNF, IL-1β, IL-6, and PGE2, which contributes to the characterization of obesity as a state of chronic low-grade inflammation." (PMID 33859943, 2021). "Gender, BMI, obesity, OSA, AHI, ODI, ESS score and EDS as well as circulating TNF-α levels were similar." (PMID 34362196, 2021). "In this respect, oral administration of FX (0.2, 0.4, and 0.6 %) was effective in reducing inflammation through reduction in IL-1β, TNF-α, iNOS, and COX-2 in a model of high-fat diet-induced obesity." (PMID 34677429, 2021). "It has been shown that enhanced TNF-α levels lead to insulin resistance and that the inhibition of TNF-α ameliorates obesity-induced insulin resistance." (PMID 34360840, 2021). "Indeed, obesity and the expansion of adipose tissue have been described to increase M1 “classically activated” macrophage infiltration as well as the production of pro-inflammatory cytokines, which is in line with the increased F4/80 and TNFα expression upon WSD in our current study." (PMID 33498469, 2021).
Obesity (continued). "As an inflammatory state characterizes obesity and IR, we evaluated the gene expression of cyclooxygenase-2 (COX-2), TNF-α, IL-6, nuclear factor kappa B (NF-κB) and inhibitor of kappa B (IκB) by RT-qPCR in the liver." (PMID 34572325, 2021). "Since plant miRNAs could suppress TNF-α signaling pathway, it would be interesting to explore if they could modulate intestinal immune system and gut barrier permeability, and if this effect would eventually contribute to the reduction of inflammation in metabolic tissues during obesity development." (PMID 33768107, 2021). "JNK inhibition reduces the release of IR-related pro-inflammatory cytokines such as TNFα and MCP-1 and represents an attractive opportunity to improve metabolic dysfunction in obesity by preventing excessive adiposity, insulin resistance and inflammation." (PMID 33805912, 2021). "Significant alterations in chronic inflammation, particularly driven by persistent innate cytokine responses from adipocytes including IL-6, TNF-α, Type 1 IFN, and Leptin (modified from Alarcon, 2021), have been noted in the setting of obesity." (PMID 34835041, 2021). "The influence of TNF receptors and ligands on protection against metabolic complications in obesity, especially T2DM, is also due to blocking the effects of TNF-a." (PMID 34572446, 2021). "Adipocytes produce and secrete the adipocytokines tumor necrosis factor-alpha (TNF-a), interleukin (IL)-6, and leptin (LEP), the levels of which are directly related to the degree of obesity." (PMID 34944525, 2021). "One of the first observations connecting AT inflammation to insulin resistance and obesity dates from studies on tumor necrosis factor (TNF)-α and efficacy of anti-TNF-α treatment in obese rodents." (PMID 33919858, 2021). "Cells from infant of mothers with obesity showed mRNA (i.e., miR-1301, miR-221, miR-155) and PPAR-γ expression inhibition, and inflammatory cytokine (IL-6, IL-1β, TNF-α) expression upregulation." (PMID 34835958, 2021). "For example, in 97 patients with obesity underwent either RYGB or biliopancreatic diversion with duodenal switch, decreased levels of IFN-γ, hs-CRP, TNF-α, IL-13, IL-6, IL-1ra, C3, and leptin were described compared with baseline levels at 1-year follow-up55." (PMID 34108550, 2021). "PVA and alginate nanofibers can modulate obesity, reduce blood glucose levels, and reduce serum levels of insulin, ALT, ALP, GGT, creatinine, TNF-α, and IL-1β in diabetic rats." (PMID 34083930, 2021). "The levels of serum fibrinogen and other acute phase reactants, such as TNF-α, IL-6, and CRP were demonstrated to be increased in obesity." (PMID 34176464, 2021). "In our study, upregulated NEU1 offset the effects of miR-23b-3p on body weight, fat percent, FBG, FI and AUC of both OGTT and ITT, and inflammatory factors (CRP, IL-6, TNF-α, MCP1) in mice with obesity-induced IR." (PMID 33781239, 2021). "In our study, we saw a significant increase in the expression of TNF-α, resistin, and IL-10 by adipocytes isolated from ING and RP depots, as a consequence of the HF diet-induced obesity." (PMID 33652751, 2021). "A direct comparison of profiles at T1 and T3 shows a lack of remodeling within promoter and enhancer regions that regulate cytokine-signaling (TNF), myeloid cell activation (CD80), and immune effector process (HLA-DRA) in monocytes from subjects with obesity." (PMID 34195568, 2021). "It should be noted that proinflammatory cytokines such as TNF-α, IL6, and IL1β may promote the disruption of lipid metabolism resulting in systemic inflammation, and that COVID-19 itself has been associated with dyslipidemia, which may worsen obesity-associated dyslipidemia." (PMID 34281182, 2021). "Systemic knockout of TNF-α, IL-6 or TNFR1 all prevent obesity-induced cancer formation in HCC and PDAC suggesting a functional role of the immune apparatus." (PMID 33987528, 2021).
Obesity (continued). "Thus, the TNF signaling pathway, which plays a substantial role in cell differentiation, apoptosis, the modulation of immune responses, and the induction of inflammation, could be a critical target of CR in treating obesity." (PMID 34360840, 2021). "Studies show that TNF-α positively regulates the expression of PAI-1, which suggests that high levels of this activator are related to the chronic inflammatory state of obesity." (PMID 33183383, 2021). "The higher levels of free fatty acids, coupled with higher levels of other inflammatory mediators like TNFα, IL6, and IL-1β will lead to the development of insulin resistance which can develop in obesity." (PMID 34804028, 2021). "First of all, glucose uptake is essential for the thermogenesis process and, in a state of obesity, pro-inflammatory signaling can alter BAT insulin sensitivity through a complex TNFα-mediated mechanism." (PMID 33805912, 2021). "In obesity, IR is demonstrated by the downregulation of IRS2 and persistent expression of IRS1, and inflammatory cytokines including TNF-α downregulate IRS2 mRNA expression." (PMID 34135978, 2021). "Expression levels of both TNF-α and TNF-α receptor 2 are upregulated during obesity and correlate with hyperinsulinemia." (PMID 33714202, 2021). "Acute-phase protein CRP is synthesized by hepatocytes and released into the circulation in response to inflammatory stimuli, including TNF and IL-6, synthesized by WAT macrophages and adipocytes in obesity." (PMID 34834553, 2021). "Besides, recent studies suggested that obesity related-excess adipose tissue could promote the neoplasia and progression of tumor through adipose tissue inflammation (circulating cytokines such as TNF-α and IL-6)." (PMID 35096970, 2021). "Obesity-induced chronic inflammation has been detected in obesity-induced IR, and some inflammatory cytokines such as CRP, IL-6, TNF-α, and MCP1 are found in obesity-induced IR." (PMID 33781239, 2021). "So far, both experimental and clinical studies have shown that CD8+ lymphocytes can increase the production of pro-inflammatory factors, e.g., TNF-α, interleukin 2 (IL-2), IFN-γ and RANTES chemokines, contributing to inflammation in the course of obesity." (PMID 34564433, 2021). "High plasma leptin in subjects with obesity, along with CXCL-10 and TNF-α, is a predictor of COVID-19 severity and disease progression." (PMID 34373739, 2021). "Together with KC, the cytokines TIMP-1, TNFα and IFN-γ, and the chemokines MCP-1 and BCA-1, key players in chronic systemic inflammation occurring in diabetes and obesity, were the most abundant." (PMID 34571976, 2021). "A parallel study has reported that inflammatory factors such as TNF-α decreased after GLP-1 analog treatment in patients with diabetes and obesity." (PMID 34283904, 2021). "The study also aims to explore inflammatory factors like MCP-1, IL-1, TNF-α and growth factor VEGF in rats with different burn severities at different levels of obesity." (PMID 33354433, 2020). "Another GLP-1 receptor agonist exenatide inhibited TNF-α and monocyte chemotactic protein-1 (MCP-1) levels and F4/80 expression in the testes of mice with high-fat diet-induced obesity." (PMID 33274238, 2020). "Obesity-related HFpEF obtained in our experimental conditions was associated with a subclinical pro-inflammatory status highlighted by significantly increased IL-6 and leptin plasma levels, a trend for increased TNF-alpha and decreased adiponectin/leptin ratio, but without CRP modifications." (PMID 33142857, 2020). "We hypothesized that the three most common characteristics of OSAS (severity of OSAS, sex, and obesity) may have an interaction effect on the risk of cardiovascular events as determined by the serum levels of the three most representative inflammatory markers (CRP, IL-6, and TNF-α)." (PMID 32629899, 2020).
Obesity (continued). "Moreover, obesity status is associated with insulin resistance, higher blood free fatty acids, and chronic micro-inflammatory status, which mediated and affected by several pro-inflammatory cytokines, such as C-reactive protein (CRP) and tumor necrosis factor-α." (PMID 33552985, 2020). "The production of inflammatory mediators, including monocyte chemoattractant protein-1 (MCP-1), interleukin (IL)-6, IL-1β, and tumor necrosis factor (TNF)α, increases with obesity since macrophages contribute to the production of them." (PMID 32019160, 2020). "For example, in epididymal WAT and in response to diet-induced obesity, DUSP5 functions as the feedback regulator of TNFα-evoked ERK1/2 signaling, which results in increased inflammatory gene expression." (PMID 32872540, 2020). "Other inflammatory markers such as TNF-α, ICAM-1, and E-selectin with a proven relationship with obesity and its complications in adults and adolescents have also not been studied." (PMID 33081030, 2020). "Elevations in circulating pro-inflammatory adipokines, such as TNF-α, PAI-1, and MCP-1, contribute to low-grade systemic inflammation and enhanced insulin resistance in obesity." (PMID 32012199, 2020). "IL-6 and TNF-α enhance the hepatic production of C-creative protein (CRP), which is increased under conditions of obesity." (PMID 32948162, 2020). "In serum and synovial fluid, eight obesity-induced inflammatory cytokines (VEGF, MIP-1α, MIP-2, IP-10, IL-1α, TNF-α, MCP-1, and leptin) and LPS were increased in the DIO-KOA group compared with the control group." (PMID 32724821, 2020). "IL-17 belongs to a family of proinflammatory cytokines, and its role in the pathogenesis of obesity is as important as that of IL-1, IL-6, IFN, or TNF-alpha." (PMID 32587472, 2020). "Factorial analysis showed that burn and obesity factors had an interactive effect on the expression of TNF-α gene on days 1 and 3, when the level of TNF-α in the obese group was higher than the overweight and normal weight groups (P < 0.05)." (PMID 33354433, 2020). "Pro-inflammatory markers, such as interleukin-6 (IL-6), tumor necrosis factor α (TNFα), and C-reactive protein (CRP), elevate in response to infection, tissue damage, and in active stressed states such as obesity." (PMID 33004039, 2020). "In our study, increased levels of resistin, TNF-α, IL-1β, and IL-6 were observed in the spleen in DIO mice, which suggested that the changes of cytokine in the spleen in obesity were indicative of altered immune functions." (PMID 32104715, 2020). "Obesity is related to increases in the levels of insulin, insulin-like growth factor (IGF), and adipocyte-derived factors such as tumor necrosis factor (TNF)-alpha, leptin, and interleukin (IL)-6 and a decrease in levels of adiponectin." (PMID 32466596, 2020). "ECs pretreated with Tumor Necrosis Factor (TNF)-α, known to be increased during obesity, displayed higher levels of miR-155." (PMID 32907629, 2020). "In obesity, adipose tissue exhibited the lower activities of antioxidant enzymes (CAT, SOD, and GSH-Px) and the higher levels of cytokines (TNF-α, IL-1β, and IL-6) and ROS generation." (PMID 32104715, 2020). "Numerous studies have demonstrated that HFD feeding and obesity contribute to increases in circulating cytokines and acute phase proteins such as CRP, TNFα, and IL-6." (PMID 32823541, 2020). "Weight loss and therapies targeting HC, TNF-α and CCL2, whether separately or in combination, may be beneficial to modulate rates of CSF secretion and/or resistance to CSF drainage pathways, both factors likely contributing to the raised ICP observed in female IIH patients with obesity." (PMID 32036786, 2020). "The intensive secretion of IL-6, TNF-α, and MCP-1 sustains the unbalanced inflammation on individuals with obesity." (PMID 32849309, 2020). "M1 pro‐inflammatory macrophages induced the secretion of IL‐1β, IL‐6, IL‐12, TNF‐α, CCL5 and CCL2 in adipose tissue during obesity." (PMID 32458441, 2020).
Obesity (continued). "Therefore, in obesity-related high plasma leptin conditions, inflammation would occur when signal transduction pathways was activated, such as the activation of NFκβ, by the binding of leptin to its receptor and subsequent release of the inflammation factors, for instance TNFα." (PMID 32824322, 2020). "M1 macrophages release pro-inflammatory and chemokines, such as TNF-α, IL-6, and MCP-1, which can directly promote the migration of macrophages and further promote obesity-induced inflammation." (PMID 33298044, 2020). "In obesity, activated WAT and the resident macrophages secrete inflammatory cytokines, such as TNF-α, IL-6, and IL-1β into the bloodstream, which stimulates hepatocytes and Kupffer cells." (PMID 33187321, 2020). "It is reported that alone acupuncture on the ST36 acupoint can decrease the leukocyte infiltration to adipose tissue and attenuates inflammatory response by reducing serum levels of TNF-α, IL-6, and IL-1 in HFD-induced obesity rats." (PMID 32724821, 2020). "The hyperlipidemia characteristic of obesity inundates TLR4 in adipose tissue macrophages, which leads to an M1-like phenotype that includes release of pro-inflammatory cytokines, such as TNF and IL-6." (PMID 33353562, 2020). "Our results came in concordance with the literature and other previous studies regarding TNF-α levels in class II and III obesity groups." (PMID 32893859, 2020). "As obesity, induced by a state of high caloric intake, is associated with chronic inflammation, we next examined whether the pro-inflammatory cytokines IL6 and TNFα levels were altered in by HF diet in gWAT, iWAT, iBAT and PAT compared to their chow-fed counterparts." (PMID 32580292, 2020). "PTEN can be upregulated in obesity to create IR via free fatty acids (FFA) and several pro-inflammatory cytokines such as Tumor Necrosis Factor alpha (TNFα) and resisting." (PMID 32582754, 2020). "An increase in the levels of pro-inflammatory cytokines and proteins such as interleukin-6 (IL-6), tumor necrosis factor alpha (TNF-α), leptin or C-reactive protein (CRP) in both blood and adipose tissue itself was observed as obesity progressed." (PMID 32555600, 2020). "Herein, data presented in our study highlight the alterations in the serum levels of TNF-α, CRP, IL-6, IL-12, sVCAM-1 and sICAM-1 with the progression of obesity among Egyptian females." (PMID 32893859, 2020). "In the same study, overexpression of lamin A/C in mouse macrophages revealed chronic inflammation by upregulation of mediators like IL6, TNFα and CCL2 and the development of obesity-induced insulin resistance." (PMID 32872320, 2020). "Although the etiology of obesity and IBD is different, both are characterized by gut inflammation with common inflammatory pathways including TNFα, IL6, and IL1b54–57." (PMID 32999402, 2020). "Pro-inflammatory cytokines, including interleukin (IL)-1, IL-6, and tumor necrosis factor (TNF)-α, are related to insulin resistance and metabolic syndromes, such as obesity and T2DM." (PMID 32699185, 2020). "Early markers of inflammation, including tumor necrosis factor-alpha (TNF-α) and microglial activation, are present in the arcuate nucleus of the hypothalamus in animal models of obesity." (PMID 32120798, 2020). "Obese mice produce high levels of proinflammatory cytokines, including TNF- α, IL-1 β, IL-6, and PAI-1, in liver and adipose tissue, and obesity is characterized by infiltration and activation of immune cells in liver and adipose tissues." (PMID 33551809, 2020). "Given that IFNγ and TNFα were determined to be top transcriptional regulators in HFD mice, it is likely that M1 macrophages are strongly activated in obesity." (PMID 33379198, 2020). "In randomized controlled trials, curcumin supplementation reduced serum IL-1β and IL-4 in adults with obesity (1 g/d for 8 wk) and reduced serum IL-6, MCP-1, and TNF-α concentrations in subjects with metabolic syndrome (1 g/d for 4 wk)." (PMID 32211803, 2020).